SVIL (supervillin)
Diseases named in the same sentence as SVIL in open-access papers:
SVIL is named in the same sentence as 35 diseases in open-access papers, as found by Europe PMC text mining. Sharing a sentence is not in itself a finding about the gene and the disease. The quoted sentences say what the papers report.
breast carcinoma (3 papers, 2019 to 2022). "For example, SVIL is intricately involved in tumour angiogenesis in liver cancer, whilst ITGAV silencing has proven to inhibit the cell proliferation and invasion of breast cancer cell lines and CDH5 has been demonstrated as a biomarker of metastatic breast cancer." (PMID 35682908, 2022). "In breast cancer cells, using stable isotope labeling by amino acids in cell culture (SILAC), SK1 has been shown to interact with key proteins that regulate cell motility (supervillin), cell adhesion and migration (myristoylated alanine-rich C-kinase substrate (MARCKS)-related protein)." (PMID 34043703, 2021).
lung carcinoma (3 papers, 2015 to 2023). "SVIL (supervilin) (GB:hypomethylated) is involved in actin-myosin and cell spreading, a plausible but unexpected finding in lung cancer as well." (PMID 26683690, 2015).
bladder cancers (2 papers, 2021 to 2023). "Among patients with diagnosed bladder cancer, high SVIL expression was significantly and positively associated with poorer OS (HR = 2.08, 95% CI 1.55–2.78, p < 0.001)." (PMID 37670039, 2023). "Univariate and multivariate Cox regression analyses showed that elevated SVIL expression was an independent risk factor for prognosis in bladder cancer." (PMID 37670039, 2023). "However, in bladder cancer tissues, the high expression of SVIL is significantly associated with poor prognosis." (PMID 37670039, 2023). "It is worth noting that our current research data provide evidence that SVIL is involved in regulating immune invasion in the local TME of bladder cancer." (PMID 37670039, 2023). "We verified the expression of SVIL in bladder cancer tissue and its corresponding surrounding normal tissue (SNT) (n = 8)." (PMID 37670039, 2023). "Our work determined that the expression of SVIL in bladder cancer tissue was significantly lower than that in normal tissue." (PMID 37670039, 2023). "In bladder cancer, high expression of SVIL was closely related to the late case stage and poor prognosis, including OS, DSS, and DFS." (PMID 37670039, 2023). "We verified the expression of SVIL in bladder cancer cell lines (T24, RT4, 5637, UMUC-3, and J82) and human ureteral epithelial immortalized cells (SV-HUC-1)." (PMID 37670039, 2023). "But interestingly, SVIL expression in bladder cancer tissues of higher T-stage group is higher than that of lower T-stage group." (PMID 37670039, 2023). "The mRNA expression of SVIL in bladder cancer was significantly downregulated compared with that in normal tissues (red arrow)." (PMID 37670039, 2023). "But the function and mechanism of SVIL in bladder cancer should be verified using a considerable number of in vivo and in vitro experiments." (PMID 37670039, 2023). "In this research, we evaluated the relationship between SVIL expression and bladder cancer in public dataset and examined the expression of SVIL in bladder cancer cell lines, tissue microarrays and patients in our cohort." (PMID 37670039, 2023). "As the expression of SVIL in high-grade bladder cancer patients is higher than that in low-grade bladder cancer patients, it is related to the infiltration of macrophages, eosinophils, and mast cells at higher levels, resulting in a poor immune state." (PMID 37670039, 2023). "In contrast, in tumor tissues from patients with bladder cancer, elevated levels of SVIL expression were positively correlated with poorer clinicopathological features of bladder cancer." (PMID 37670039, 2023). "In general, this study not only highlights the importance of SVIL in bladder cancer but also demonstrates its potential as a prognostic biomarker and therapeutic target for bladder cancer." (PMID 37670039, 2023). "To further explore the potential role of SVIL in bladder cancer, based on TCGA-BLCA dataset, we performed GO, KEGG analysis of SVIL co-expressed genes and GSEA analysis of SVIL." (PMID 37670039, 2023). "Three of the novel missense mutational cancer genes were mutated at >1% in their respective TCGA cancer types: ATP10D (9.4% in melanoma), SVIL (3.2% in ovarian carcinoma) and WDR36 (3.2% in bladder carcinoma)." (PMID 34313788, 2021). "In addition, elevated SVIL expression levels in tissues of bladder cancer patients also had statistically significant correlation with poorer OS, DFS, and DSS in bladder cancer as well." (PMID 37670039, 2023). "However, the expression of SVIL in bladder cancer and its functional relationship with tumors has not yet been reported." (PMID 37670039, 2023). "However, the mechanism of SVIL in bladder cancer has not been reported yet." (PMID 37670039, 2023). "The absence of SVIL may promote or accelerate the occurrence of bladder cancer." (PMID 37670039, 2023).
cardiomyopathies (2 papers, 2017 to 2025). "Loss of supervillin leads to impaired myofibrillar cytoskeleton and formation of autophagic vacuoles, which is responsible for cardiomyopathy with altered proteostasis and myofibrillar disorganization." (PMID 41144497, 2025). "Subsequently, the effect of SVIL on other genes associated with cardiomyopathy was assessed by western blot analysis." (PMID 41144497, 2025).
cervical carcinoma (2 papers, 2018 to 2023). A carcinoma arising from either the exocervical squamous epithelium or the endocervical glandular epithelium. "As has been described previously in HeLa cervical carcinoma cells, supervillin knockdown with RNAi #2 or #3 decreased Rac1 loading in normoxia." (PMID 29954442, 2018).
ovarian carcinoma (2 papers, 2021 to 2025). A malignant neoplasm originating from the surface ovarian epithelium. "For instance, SVIL promotes ovarian cancer progression and EMT under hypoxic conditions via the TGF-β/Smad pathway." (PMID 40447667, 2025).
Arterial thrombosis (1 paper, 2014). The formation of a blood clot inside an artery. "Recently, a study suggested an inhibitory role for SVIL in platelet adhesion and arterial thrombosis using human GWAS and mice knockout approaches." (PMID 24592274, 2014).
autoimmune disease (1 paper, 2025). A disorder resulting from loss of function or tissue destruction of an organ or multiple organs, arising from humoral or cellular immune responses of the individual to their own tissue constituents. "QTLs were mapped to correspond to SHAe endogenous loci associated with human autoimmune diseases, such as the one proximal to the SVIL locus that is linked to CD and inflammatory bowel disease (IBD) (GitHub Repository)." (PMID 40131776, 2025).
dilated cardiomyopathy (1 paper, 2024). Cardiomyopathy which is characterized by dilation and contractile dysfunction of the left and right ventricles. "scGO also identified CUX1, SOX6, and SVIL, which have been reported as pivotal factors implicated in causing dilated cardiomyopathy." (PMID 39820437, 2024).
endometrial cancer (1 paper, 2025). Primary or metastatic malignant neoplasm involving the endometrium (mucous membrane that lines the endometrial cavity). "We have identified the expression levels of GSN, CAPG, AVIL, SVIL, and FLII as independent survival risk factors in endometrial cancer (EC) patients." (PMID 39964147, 2025). "The low expression of CAPG, AVIL, and SVIL, together with the high expression of GSN, VILL, and FLII, were found to be significantly associated with poor overall survival in endometrial cancer patients." (PMID 39964147, 2025).
endothelial dysfunction (1 paper, 2024). In vascular diseases, endothelial dysfunction is a systemic pathological state of the endothelium (the inner lining of blood vessels) and can be broadly defined as an imbalance between vasodilating and vasoconstricting substances produced by (or acting on) the endothelium. "JCAD has been previously implicated in endothelial dysfunction, pathological angiogenesis, and atherosclerotic plaque formation, whereas the role of SVIL in cardiovascular disease remains unknown, but it may promote angiogenesis and epithelial to mesenchymal transition." (PMID 38776872, 2024).
familial cardiomyopathy (1 paper, 2025). An instance of cardiomyopathy that is caused by an inherited modification of the individual's genome. "As expected, SVIL knockdown markedly decreased the levels of caveolin-3 and α-sarcoglycan which were previously identified in familial cardiomyopathy." (PMID 41144497, 2025).
germinoma (1 paper, 2010). A malignant germ cell tumor arising in the central nervous system. "In the germinoma group, the expression levels of RUNX1T1 and THRB were inversely correlated with expression of miR-146a, and the levels of NRP1, SVIL and PDGFRA were inversely correlated with the expression of miR-142-5p." (PMID 20178649, 2010).
glioma (1 paper, 2023). A benign or malignant brain and spinal cord tumor that arises from glial cells (astrocytes, oligodendrocytes, ependymal cells).
heart failure (1 paper, 2025). Inability of the heart to pump blood at an adequate rate to meet tissue metabolic requirements. "All these observations revealed that the loss of SVIL could play a role in the pathogenic process of heart failure." (PMID 41144497, 2025).
hypertrophic cardiomyopathy (1 paper, 2026). A condition in which the myocardium is hypertrophied without an obvious cause. "SVIL encodes supervillin, an actin-binding protein with prior genetic evidence for associations with hypertrophic cardiomyopathy and descending aorta diameter." (PMID 41419686, 2026).
neuroblastoma (1 paper, 2018). Neuroblastoma (NB) is the most common solid, extracranial childhood tumor. "In neuroblastoma cells, an isoform of LSD1 called LSD1+8a complexes with Supervillin protein (SVIL) and other co-factors." (PMID 29515779, 2018).
osteosarcoma (1 paper, 2018). A usually aggressive malignant bone-forming mesenchymal neoplasm, predominantly affecting adolescents and young adults. "To create cells with and without high concentrations of defined supervillin isoforms, we transfected U2OS osteosarcoma or RH30 rhabdomyosarcoma cells with plasmids encoding EGFP-hSV1, EGFP- or Flag-tagged hSV4, or GFP-mSV2 (murine supervillin, isoform 2; archvillin; MAV)." (PMID 30332471, 2018).
prostate carcinoma (1 paper, 2023). A carcinoma that arises from epithelial cells of the prostate gland. "The human SVIL gene is localized to a single chromosomal locus at 10p11.2, a region that is deleted in some prostate cancers, implying that deletion of this gene may be closely associated with the development of some prostate cancers." (PMID 37670039, 2023).
Sepsis (1 paper, 2025). Sepsis is defined as life-threatening organ dysfunction caused by a dysregulated host response to infection. "Key genes identified among these, such as FARSA, SVIL, LAMP2, and COL12A1, were found to be influenced by exercise in both burns and sepsis, suggesting their potential roles in exercise-mediated recovery processes." (PMID 40028316, 2025).
Thrombocytopenia (1 paper, 2023). A reduction in the number of circulating thrombocytes. "At the functional level, depletion of SVIL and SHANK3 inhibited megakaryopoiesis and thrombopoiesis, while overexpression of SVIL rescued the inhibitory effect of serine-mediated thrombocytopenia." (PMID 37055385, 2023).
tumor (10 papers, 2015 to 2025). "Among the eight gelsolin superfamily genes, CAPG, VILL, and SVIL showed high associations with immune cell infiltration, highlighting their crucial roles in the tumor microenvironment (TME) and immunological function." (PMID 39964147, 2025). "Supervillin is an actin and membrane-associated protein that has been implicated in each step of tumor cell migration and metastasis." (PMID 29954442, 2018). "In 124 HCC specimens, supervillin expression levels were dramatically upregulated, compared to those in adjacent non-tumor specimens or normal liver tissues." (PMID 29954442, 2018). "Consequently, clinicopathological characteristics and the expression levels of GSN, SCIN, CAPG, VILL, VIL1, SVIL, and FLII were found to be closely associated with tumor stages in EC." (PMID 39964147, 2025). "For example, SVIL can promote cancer cell survival by regulating the level of p5311, or in response to signals of intratumoral hypoxia, thereby increasing its own expression, ultimately leading to tumor metastasis and poor survival in liver cancer." (PMID 37670039, 2023). "In the present study, we found that SVIL was differentially expressed in different tumor types." (PMID 37670039, 2023). "However, in advanced tumors, tumor aggressiveness and proliferative activity are significantly increased, which may prompt higher expression of supervillin in advanced tumor cells to maintain cell division and promote tumor cell invasion into the muscle layer." (PMID 37670039, 2023). "Notably, the higher expression of supervillin was positively correlated with the presence of PVTT, which suggested that supervillin production might be induced by the hypoxic tumor microenvironment." (PMID 29954442, 2018). "SVIL and FGG also have corresponding roles in the tumor process." (PMID 36160006, 2022). "In a mouse model, HAL treatment enhanced total tumor growth and lung metastasis with control, but not with supervillin knockdown, HCC cells." (PMID 29954442, 2018). "Supervillin expression is dramatically increased in HCC tumor specimens, compared to adjacent non-tumor specimens or normal liver tissues." (PMID 29954442, 2018).
cancer (8 papers, 2018 to 2025). A tumor composed of atypical neoplastic, often pleomorphic cells that invade other tissues. "Conversely, CAPG, AVIL, and SVIL expression negatively correlated with anticancer immune cells and positively correlated with immunosuppressive cells like TAMs, Tregs, Th2 cells, MDSCs, and cancer‐associated fibroblasts (CAFs)." (PMID 39964147, 2025). "To determine the overall expression levels of SVIL in different malignancies, we first analyzed SVIL expression in different cancer types using the TIMER database." (PMID 37670039, 2023). "Hypoxia-induced increase in supervillin expression is a significant and independent predictor of cancer metastasis, which leads to poor survival in HCC patients." (PMID 29954442, 2018). "Hypoxia-induced upregulation of supervillin promoted cancer cell migration and invasion via the activation of the ERK/p38 pathway downstream of RhoA/ROCK signaling." (PMID 29954442, 2018). "The results of the current study demonstrated that hypoxia elicits an upregulation in the expression of supervillin, which was a significant and independent predictor of cancer metastasis and poor survival in HCC patients." (PMID 29954442, 2018). "Here, we provide evidence that hypoxia-induced upregulation of supervillin promotes cancer cell migration and invasion while increasing the activation of RhoA." (PMID 29954442, 2018). "Cancer cells contain at least three supervillin isoforms (SV1, SV4, and SV5)." (PMID 29954442, 2018). "Moreover, supervillin promotes cancer cell survival through integrin-based adhesions via its crosstalk between ERK-mediated survival signaling and cell motility pathways that contribute to ERK signaling." (PMID 29954442, 2018). "Given that the EMT program is critical for matrix invasion and the dissemination of most and possibly all carcinoma types, we examined whether supervillin expression induces EMT in hypoxic HCC cell lines." (PMID 29954442, 2018). "Specific interactions between SNAREs and Munc18c, gelsolin, supervillin, as well as other unidentified SNARE regulatory proteins, represent potential targets to combat metastasis in patients with invadopodia-forming cancer subtypes." (PMID 34094984, 2021).
myopathy (3 papers, 2023 to 2025). A disease of the muscle in which the muscle fibers do not function properly. "It is worth noting that loss of supervillin has been reported in four myopathy patients presented with myofibrillar structural abnormalities." (PMID 41144497, 2025). "Increased abundance of supervillin might reflect the same hypothesis as loss of expression of functional supervillin was linked to the manifestation of myopathy characterized by myofibrillar disorganization and build-up of protein aggregates." (PMID 36692708, 2023). "The protein expressed by SVIL is important for the integrity of human muscle fibers, and its deletion leads to myopathy with myofibrillar disorganization." (PMID 37670039, 2023).
SVIL also shares sentences with these, for which no sentence is quoted: cardiovascular disease (2 papers); hepatocellular carcinoma (2); adenocarcinoma (1); atherosclerosis (1); CNS germinoma (1); cystinuria (1); inflammatory bowel disease (1); left ventricular hypertrophy (1); liver cancer (1); melanoma (1); Skeletal myopathy (1).